PRF1 (perforin 1)
Diseases named in the same sentence as PRF1 in open-access papers (continued):
Sharing a sentence is not in itself a finding about the gene and the disease.
atherosclerosis (2 papers, 2013 to 2023). A disease characterized by the build-up of fatty material and calcium deposition in the arterial wall resulting in partial or complete occlusion of the arterial lumen. "To further investigate the role of GzmB and Prf1 in the development of atherosclerosis in ApoE KO mice, we generated GzmB/ApoE DKO and Prf1/ApoE DKO mice." (PMID 24205352, 2013). "In this study, we investigated the role of both GzmB and Prf1 in the pathogenesis of atherosclerosis." (PMID 24205352, 2013). "In conclusion, both Prf1 and GzmB contribute to the pathogenesis of atherosclerosis in ApoE KO mice." (PMID 24205352, 2013). "We also generated GzmB/ApoE double knockout (DKO) mice and Prf1/ApoE DKO mice to investigate the potential roles of these twoproteins in atherosclerosis." (PMID 24205352, 2013). "The present study suggests that Prf1 and GzmB exert unique roles in the onset and progression of atherosclerosis." (PMID 24205352, 2013). "Other studies have also investigated the role of GzmB and Prf1 in atherosclerosis.One study by Viswanathanet al showed that GzmB/ApoE DKO mice exhibit a trend towards reduced plaque development compared to ApoE KO mice in a model of aortic allograft vasculopathy." (PMID 24205352, 2013). "In the present study, we observed similar staining for GzmA in the plaques of ApoE KO, GzmB/ApoE DKO and Prf1/ApoE DKO mice.The exact role of GzmA and its influence on inflammation and plaque development in atherosclerosis remains to be investigated." (PMID 24205352, 2013). "In addition to Dpp4, there was an upregulation of a number of inflammation‐related genes including Card8, Card16, Gzma, Prf1, Il2rg, Il32, Cd52, and Ccl4 in CD4+ T cells isolated from patients with atherosclerosis." (PMID 36683148, 2023). "Therefore, as many of these ECM proteinsare well-described GzmB substrates, it is possible that the role of GzmB in atherosclerosis pathogenesis is not limited exclusively to Prf1-dependant intracellular apoptosis, but could potentially include ECM remodelling events as well." (PMID 24205352, 2013).
dengue (2 papers, 2022 to 2024). "Features of hyperinflammation are associated with dengue severity, including higher biomarkers, impaired NK cell function, and polymorphisms in NK cell cytolytic function genes (KLRK1 and PRF1)." (PMID 35267010, 2022). "However, a novel PRF1 SNP at position Chr10:70598899 (rs885821) was more prevalent in patients with grade 1 and 2 dengue compared to those with grade 0 (35%, 25%, and 10%, respectively)." (PMID 35267010, 2022).
familial cancer (2 papers, 2011 to 2020). "A search for PRF1 mutations was conducted in a total number of 89 probands identified in familial cancer clusters." (PMID 21936944, 2011). "In addition to mutations associated with risk of hereditary cancer, pathogenic/likely pathogenic mutations were detected in ERCC2 (n = 1), FANCA (n = 1), FANCC (n = 1), HNF1A (n = 1), PRF1 (n = 1) RECQL4 (n = 2), WRN (n = 1), and XPA (n = 1)." (PMID 31963545, 2020).
Hepatitis (2 papers, 2017 to 2018). Inflammation of the liver. "To test whether pharmacological inhibition of perforin-1 in vivo can influence the course of T cell-mediated hepatitis, we treated AdGOL-infected mice that received OT-I T cells with the perforin-1 inhibitor SN34960, starting on day 1 after infection." (PMID 30442932, 2018).
metastatic tumors (2 papers, 2020 to 2021). "GZMA and PRF1 were tightly co-expressed across both primary and metastatic tumors (Spearman rank correlation, rho ~ 0.9)." (PMID 33779796, 2021).
periodontitis (2 papers, 2024). An acute or chronic inflammatory process that affects the tissues that surround and support the teeth. "Five hub ICD-related genes (ENTPD1, TLR4, LY96, PRF1 and P2RX7) were identified for the construction of a diagnostic model for periodontitis." (PMID 39555084, 2024). "In line with the findings of the validation set, our findings demonstrated that ENTPD1, TLR4, LY96, PRF1 were elevated in periodontitis patients while P2RX7 expression was decreased." (PMID 39555084, 2024). "Five key genes associated with ICD (ENTPD1, TLR4, LY96, PRF1 and P2RX7) may be diagnostic biomarkers of periodontitis and future therapeutic targets." (PMID 39555084, 2024). "In contrast to the healthy group, the periodontitis group had higher levels of ENTPD1, TLR4, LY96, and PRF1 expression and lower levels of P2RX7 expression, according to the qPCR data." (PMID 39555084, 2024). "Furthermore, we performed cell localization of PRF1 and found that it was mainly located in CD8T cells, and that both CD8T cells and PRF1 were abundantly activated in periodontitis samples, further confirming the existence of ICD." (PMID 39555084, 2024).
Primary hemophagocytic lymphohistiocytosis (2 papers, 2022 to 2024). "Rare heterozygous missense variants in genes responsible for primary hemophagocytic lymphohistiocytosis (LYST, STXBP2, PRF1, UNC13D, AP3B1, and DOCK8) were found in patients with MIS-C." (PMID 38397896, 2024). "Thirty-nine children were diagnosed with MIS-C, and 25.4% of the 39 MIS-C patients harbored rare heterozygous missense mutations either in primary hemophagocytic lymphohistiocytosis (pHLH) genes (LYST, STXBP2, PRF1, UNC13D, AP3B1) or the HLH-associated gene DOCK8 (four variants)." (PMID 35336791, 2022).
primary immunodeficiency (2 papers, 2016 to 2025). "The circle plot representation of KEGG results highlighted specific enrichments: CD3E and CD8A were significantly enriched in primary immunodeficiency, while GZMB and PRF1 were notably enriched in allograft rejection." (PMID 39974584, 2025).
prostate carcinoma (2 papers, 2024 to 2025). A carcinoma that arises from epithelial cells of the prostate gland. "Accordingly, elevated PRF1 levels were detectable in the tumor, offering a novel therapeutic strategy for the treatment of advanced prostate cancer." (PMID 40691738, 2025). "In light of this challenge, PRF1 expression was introduced into target cells directly, via a liposomal nanocarrier encapsulating a PRF1 expression vector driven by the prostate-specific antigen (PSA) promoter, so PRF1 expression was restricted to the prostate cancer cells." (PMID 40691738, 2025). "Furthermore, CYThigh prostate cancer patients are more sensitive to ICIs due to the fact that high GZMA and PRF1 expression levels increase the number of CD8+ T cells and the expression of immune checkpoints, including PD-L1, compared to patients with low CYT levels." (PMID 38612436, 2024).
rheumatic diseases (2 papers, 2015 to 2021). "We identified a total of eight differentially expressed genes (TNFSF10, CX3CR1, LY96, TLR5, TXN, TIA1, PRKCH, PRF1), each associated with at least 3 of the 4 studied rheumatic diseases." (PMID 26352601, 2015). "A previous study indicated the importance of PRF1 in immune response and immune regulation related functions in AS and highlighted its significance of common markers for rheumatic diseases." (PMID 34589304, 2021). "By jointly analyzing 6 published microarray gene expression datasets about RA, SLE, OA and AS, we identified eight genes (TNFSF10, CX3CR1, LY96, TLR5, TXN, TIA1, PRKCH, PRF1) presenting general importance to rheumatic diseases." (PMID 26352601, 2015).
Still’s disease (2 papers, 2008 to 2026). "In the present study we therefore hypothesized that defective apoptosis in patients with systemic-onset JIA could be due to polymorphisms in the genes PRF1, GZMB, UNC13D, or Rab27a." (PMID 18311812, 2008). "In conclusion, we could not detect an association between SNPs in PRF1, GZMB, UN13D, or Rab27a and an increased risk of susceptibility to systemic-onset JIA." (PMID 18311812, 2008).
Thrombocytopenia (2 papers, 2012 to 2023). A reduction in the number of circulating thrombocytes. "All Prf1 KO mice infected with DN-SCP-MCMV developed a severe illness with profound leukopenia and thrombocytopenia (Figure A1A in Appendix)." (PMID 22891066, 2012).
tuberculosis (2 papers, 2024 to 2025). A chronic, recurrent infection caused by the bacterium Mycobacterium tuberculosis. "Analysis of the validation set data revealed reduced levels of GZMB and PRF1 in latent tuberculosis infection (LTBI) and TB patients compared to those in HI, alongside significantly elevated expression levels of the LAG-3 and IFN-γ genes in these samples." (PMID 38957797, 2024).
acute graft versus host disease (1 paper, 2013). A syndrome of immunologically mediated tissue damage that may occur following an allogeneic transplant, usually affecting the skin, liver, and GI tract. "Finally, we analyzed methylation in IFN-γ, FASL, IL-10, and PRF1 and found association with the severity of the acute graft-versus-host disease." (PMID 23451113, 2013).
Adult onset (1 paper, 2023). Onset of disease manifestations in adulthood, defined here as at the age of 16 years or later. "Of the four genes harboring rare or low-frequency variants previously identified as associated with adult-onset MS, three (PRF1, NLRP8, and HDAC7) passed quality control and filtering steps to be included in analyses." (PMID 36755464, 2023). "These included variants within PRF1, a gene that was previously identified as associated with adult-onset MS, and two genes in the MHC region (BRD2 and AGER)." (PMID 36755464, 2023).
albinism (1 paper, 2015). A congenital disorder characterized by partial or complete absence of melanin pigment in the eyes, hair, or skin. "Unexpectedly, we found biallelic PRF1 mutations in 1 patient with albinism." (PMID 25312756, 2015).
Alzheimer disease (1 paper, 2023). A progressive, neurodegenerative disease characterized by loss of function and death of nerve cells in several areas of the brain leading to loss of cognitive function such as memory and language. "Recently, the Prf1 pathway has also been associated with different CNS diseases spanning from the eye to the brain, such as choroidal neovascularization in AMD patients, but also in mouse models of experimental stroke, TBI, Parkinson's, and Alzheimer’s diseases." (PMID 37689689, 2023).
anemia (1 paper, 2016). A reduction in the number of red blood cells, the amount of hemoglobin, and/or the volume of packed red blood cells. "Loss of control of parasitemia in infected intact mice followed a period of weight loss and anemia, which did not occur in the infected Prf1-/- mice." (PMID 27403737, 2016).
B cell lymphomas (1 paper, 2011). "These PRF1-KO mice develop spontaneous and aggressive disseminated B-cell lymphoma, and fail to efficiently reject many transplanted tumors." (PMID 21936944, 2011).
basophilic leukemia (1 paper, 2014). "However, they also report that the lytic function of perforin was not affected by over-expression of mutated PRF1 in rat basophilic leukemia." (PMID 24795715, 2014).
bladder urothelial carcinoma (1 paper, 2018). "In TCGA-ACC, non-metastatic cutaneous melanoma (“m0” TCGA-SKCM), and bladder urothelial carcinoma (TCGA-BLCA but not the GSE32894 dataset), both individual and simultaneous high levels of PRF1 and GZMA were significantly associated with better prognosis." (PMID 29515971, 2018).
bone marrow failure (1 paper, 2020). "This includes genes mutated in rare hematological syndromes (ADA, GP6, IL17RA, PRF1, and SEC23B), reported in prior MDS/AML or inherited bone marrow failure (IBMF) series (DNAH9, SH2B3, and NAPRT1), or novel loci where loss-of- function of the identified germline variants was demonstrated (DHX34)." (PMID 32098966, 2020).
cardiotoxicity (1 paper, 2025). Toxicity that impairs or damages the heart. "Those with cardiotoxicity had a noticeable increase in circulating CD4 + FOXP3 + and CD8 + PRF1 + T cells at disease onset." (PMID 41510228, 2025).
chordoma (1 paper, 2023). Chordomas are rare malignant tumors arising from embryonic remnants of the notochord in axial skeleton. "The examination of NKT and NK cells in chordoma revealed their elevated cytotoxicity, which was distinguished by the presence of PRF1, GZMB and GNLY." (PMID 37784253, 2023).
clear cell renal cell carcinoma (1 paper, 2022). "For example, although a four-gene signature (composed of NCR1, PRF1, CX3CL1 and CX3CR1) was shown to accurately distinguish NK-high vs NK-low subgroups in clear cell renal cell carcinoma, these genes are ubiquitously expressed by many immune cell types." (PMID 36685584, 2022).
co-infection (1 paper, 2016). "PRF1 was significantly lower in non-survivors (at 30 days after ICU admission) in patients with HIV co-infection (p = 0.03), but there were no other genes associated with mortality." (PMID 26871709, 2016).
cutaneous leishmaniasis (1 paper, 2024). Leishmaniasis affecting the skin. "Studies have shown that localized skin inflammation in cutaneous leishmaniasis leads to a chronic systemic IFN-γ signature, with increased expression of cytotoxic markers GZMB, Pore-forming protein 1(PRF1), and GNLY." (PMID 39342024, 2024).
cyst (1 paper, 2023). A sac-like closed membranous structure that may be empty or contain fluid or amorphous material. "The degree of the decrease in the cyst burden was calculated as the fold decreases in cerebral BAG1 levels in the recipients of the normal T cells and immune T cells from infected WT and Prf1−/− mice in comparison with the mean value of BAG1 mRNA levels in the control mice with no T-cell transfer." (PMID 37868957, 2023).
endometrial carcinoma (1 paper, 2022). A malignant tumor arising from the epithelium that lines the cavity of the uterine body. "Similarly, the negative expression of PRF1 was detected in 11 endometrial carcinoma samples." (PMID 35898926, 2022).
endometriosis (1 paper, 2023). The growth of functional endometrial tissue in anatomic sites outside the uterine body. "No direct link has been established between RBP4, G2MB, or PRF1 and endometriosis, necessitating further investigation." (PMID 37662927, 2023). "However, there is no report about the relationship between PRF1 and RBP4 and other uterine pathologies, which suggests that these two might be unique signatures of endometriosis." (PMID 37662927, 2023).
epilepsy (1 paper, 2021). A brain disorder characterized by episodes of abnormally increased neuronal discharge resulting in transient episodes of sensory or motor neurological dysfunction, or psychic dysfunction. "The PPI showed that there are six resistance genes (CD247, CTSW, IL2RB, MATK, NKG7, and PRF1) that may play a central role in the resistance of epilepsy patients." (PMID 34805265, 2021).
fibrosarcoma (1 paper, 2025). A malignant mesenchymal fibroblastic neoplasm affecting the soft tissue and bone. "For example, a preclinical study found pretreatment with trabectedin improved the response to anti–PD-1 in a murine model of fibrosarcoma and led to upregulation of CD8, GZMB, PRF1, and CXCL10 mRNA expression in trabectedin-treated tumors." (PMID 39777457, 2025).
Fulminant hepatitis (1 paper, 2018). Acute hepatitis complicated by acute liver failure with hepatic encephalopathy occurring less than 8 weeks after the onset of jaundice. "In summary, we show that fulminant hepatitis depends on a nonredundant function of perforin-1 in effector CD8 T cells." (PMID 30442932, 2018). "Mice that received Prf1−/− OT-I T cells did not have increased ALT levels and were fully protected from fulminant hepatitis." (PMID 30442932, 2018).
fulminant viral hepatitis (1 paper, 2018). Fulminant viral hepatitis is a rapid and severe impairment of liver functions (acute liver failure) with hepatic encephalopathy developing less than 8 weeks after the onset of jaundice, secondary to viral hepatitis mainly due to HBV, but also to HAV. "Rather, we found that perforin-1-dependent killing of cross-presenting LSECs is the predominant and non-redundant effector mechanism of CD8 T cells during fulminant viral hepatitis." (PMID 30442932, 2018).
gangrene (1 paper, 2018). Death of tissue, usually in considerable mass and generally associated with loss of vascular (nutritive) supply and followed by bacterial invasion and putrefaction. "Interestingly, many of the old Prf1−/− males in our study had enlarged seminal glands (in 70% of Prf1−/− mice compared to 10% in WT), which eventually resulted in gangrene." (PMID 30575733, 2018).
Glomerular sclerosis (1 paper, 2018). Accumulation of scar tissue within the glomerulus. "Additionally, in the kidney of Prf1−/− mice, periodic acid−Schiff (PAS) staining revealed enhanced formation of glomerular sclerosis compared to WT controls (P < 0.01)." (PMID 30575733, 2018).
H1N1 influenza (1 paper, 2022). "A prior respiratory pandemic pathogen, H1N1 influenza, is one such example, where heterozygous missense mutations in primary HLH genes (PRF1, LYST) were identified in 36% of fatal cases." (PMID 35336791, 2022).
head and neck cancer (1 paper, 2021). A primary or metastatic malignant neoplasm affecting the head and neck. "As an important prognostic factor, PRF1 was associated with immune infiltration in head and neck cancer." (PMID 34631788, 2021).
heart failure (1 paper, 2021). Inability of the heart to pump blood at an adequate rate to meet tissue metabolic requirements. "For the differential genes associated LMNA alone with euchromatin, we obtained 5 candidate genes (EGR2, NMB, CREBBP, PRF1, and TENM4), of which EGR2 and NMB have been reported to involve in myocardial ischemia and heart failure, respectively." (PMID 33407844, 2021).
Hyperglycemia (1 paper, 2022). An increased concentration of glucose in the blood. "According to the data, period 1b, kallikrein-11, solute carrier family 25 member 48, period 3, f-box and leucine-rich repeat protein 3, perforin-1, and carboxy-peptide A5 were identified as the common genes that functioned to resist hyperglycemia in the two strains." (PMID 36246125, 2022).
iris disease (1 paper, 2014). "Neither the Prf1 or Il2rg mutations had any influence on the iris disease, which was indistinguishable from that of their wild-type littermates." (PMID 24678736, 2014). "Our findings demonstrate that neither diminishing NK mediated cytotoxic activity (Prf1 mutation) nor NK cell depletion (Il2rg mutation) has any influence on the severity or timing of GpnmbR150XTyrp1b mediated iris disease." (PMID 24678736, 2014).
ischemic stroke (1 paper, 2021). A stroke disorder caused by obstruction of blood flow to the brain, due to thrombotic (local blood clot formation) or embolic (due to a blood clot or other material traveling from another site) event. "We identified the different subtypes of perforin+CD45+ cells in the ischemic brains of Prf1-EGFP transgenic mice from 12 h to 14 days after ischemic stroke." (PMID 34262436, 2021). "Flow cytometry was used to analyze the percentages and types of CD45+CD3+ T cells after ischemic stroke in Prf1–/– mice on at day 14 after dMCAO." (PMID 34262436, 2021). "To determine whether perforin regulates neurogenesis after ischemic stroke, we collected neural stem/progenitor cells from Prf1–/– mice on day 14 after dMCAO." (PMID 34262436, 2021). "However, the percentage of Glast–CD133–CD24+ neuroblasts increased in Prf1–/– dMCAO mice, suggesting that perforin-mediated neurotoxicity impaired neurogenesis and promoted neurotoxic astrogliosis after ischemic stroke." (PMID 34262436, 2021).
kidney transplant (1 paper, 2015). A surgical procedure in which one or both kidneys from a donor are implanted into a recipient. "The urine and peripheral blood transcript levels of PRF1 and GZMB were shown to be increased in kidney transplant recipients with acute rejection." (PMID 26286066, 2015).